HCG4B (HLA complex group 4B)
Synonyms: HCGIV-6; HCGIV.5; HCGIV-06; bCX67J3.3; Em:AB023056.16; bPG309N1.1; bQB90C11.3; formerly HCG4P6
Gene: Transcribed unprocessed pseudogene on chromosome 6 (29,925,983 to 29,926,973, reverse strand). Ensembl gene ENSG00000227262.
Diseases named in the same sentence as HCG4B in open-access papers:
HCG4B is named in the same sentence as 2 diseases in open-access papers, as found by Europe PMC text mining. Sharing a sentence is not in itself a finding about the gene and the disease. The quoted sentences say what the papers report.
psoriasis (1 paper, 2015). An autoimmune condition characterized by red, well-delineated plaques with silvery scales that are usually on the extensor surfaces and scalp. "Some of the DMRs situated on chromosome 6were in major histocompatibility complex genes, such as ring finger protein 39(RNF39), psoriasis susceptibility 1 candidate 3(PSORS1C3), and HLA complex group 4b (HCG4P6)." (PMID 29492281, 2015).
HCG4B also shares sentences with these, for which no sentence is quoted: chronic obstructive pulmonary disease (1 paper).